HGF (hepatocyte growth factor)
Diseases named in the same sentence as HGF in open-access papers (continued):
Sharing a sentence is not in itself a finding about the gene and the disease.
pulmonary arterial hypertension (5 papers, 2016 to 2024). Pulmonary arterial hypertension (PAH) is a group of diseases characterized by mean pulmonary artery pressure >20 mmHg and elevated pulmonary arterial resistance leading to right heart failure. "This could be of importance as it has been previously reported that stimulation of the hypoxia inducible factor-1 by HGF was associated with pulmonary arterial hypertension." (PMID 35066575, 2022). "Thirty-two proteins were even reported by at least five or more analyses and have known connections to age-related diseases and aging, including HGF, which has been shown to attenuate inflammation and severity of pulmonary artery hypertension in a rat model." (PMID 36289702, 2022). "The combined treatment of rats with pulmonary arterial hypertension with HGF and Ang1 can better improve the effective perfusion of newly formed microvessels and the integrity of endothelial cell adhesion junctions, exhibiting a more mature and stable phenotype of newly formed blood vessels." (PMID 39291265, 2024). "It is currently unclear whether the increased serum level of HGF is a consequence of thrombosis itself or of other factors that are involved in the cardiovascular burden including pulmonary hypertension, but further investigation may provide us the unknown information on the etiology of PH." (PMID 30594174, 2018).
silicosis (5 papers, 2018 to 2024). Silicosis is a respiratory disease caused by breathing in (inhaling) silica dust. "In sum, the results proposed MSC/HGF administration as a safe and effective treatment for silicosis." (PMID 37605719, 2023). "A clinical study on HGF/MSCs therapy for silicosis concluded that the administration of HGF/BM‐MSCs was safe and effective in some patients with silicosis." (PMID 35922965, 2022). "BM-MSCs transfected with HGF have been reported to be effective in improving pulmonary fibrosis in patients with silicosis." (PMID 29673394, 2018). "Researchers transfused autologous BM-MSCs-HGF into silicosis patients, which reduced pulmonary small nodules significantly, with pulmonary function and inflammation of patients gradually ameliorated." (PMID 29673394, 2018). "However, autologous BMSCs treated with hepatocyte growth factor can effectively improve the adverse symptoms of silicosis patients and promote the absorption of silicosis nodules." (PMID 33343360, 2020).
tendinopathy (5 papers, 2012 to 2024). "GM@HDC@HGF with synergistic antioxidant and anti-inflammatory activities were fabricated for in situ treatment of tendinopathy." (PMID 38414798, 2024). "Collectively, our findings demonstrate that smumf cells at P10, which secrete HGF, can effectively manage tendinopathy by inhibiting the NF-κB and MAPK signaling pathways in tenocytes, thereby reducing inflammation and highlighting their potential as a cell therapy." (PMID 39500862, 2024). "Thus, HGF-induced TSC CM has therapeutic potential for the treatment of tendinopathy." (PMID 33898452, 2021). "Studies using local administration of bFGF, HGF and IGF have all shown beneficial effects in the healing process of tendon injuries, but not all injuries were tendinopathies though." (PMID 22480275, 2012).
acute pancreatitis (4 papers, 2014 to 2025). An acute inflammatory process that leads to necrosis of the pancreatic parenchyma. "Recombinant human hepatocyte growth factor provided protective effects for lung injury in caerulein-induced acute pancreatitis in mice." (PMID 30515205, 2018). "The major findings were that 14 out of 47 cytokines were higher on admission in patients who developed severe pancreatitis compared with those with moderately severe or mild disease and that IL-6 and hepatocyte growth factor (HGF) were independent predictors of severe acute pancreatitis." (PMID 25673030, 2014).
allergic disease (4 papers, 2014 to 2025). An immune response that occurs following re-exposure to an innocuous antigen, and that requires the presence of existing antibodies against that antigen. "The biological actions of HGF on immune cells are likely to underlie the mechanisms by which HGF exerts its therapeutic effect on diseases associated with allergies, inflammation, and fibrosis, at least in part." (PMID 28548072, 2014). "For oncostatin-M (OSM), cystatin D (CST5) and hepatocyte growth factor (HGF) similar changes between visits were observed in both allergy groups." (PMID 40929127, 2025). "The results support the concept that IL13 and HGF have protective effects and TGFβ2 may act as a risk factor, which may explain the diversity of results from epidemiological studies on the health-promoting effects of breastfeeding with regards to allergic diseases." (PMID 28538696, 2017).
autoimmune myocarditis (4 papers, 2012 to 2020). Autoimmune myocarditis is an autoimmune disease that affects the heart. "Moreover, HGF up-regulates IL-4 and IL-10 in autoimmune myocarditis, indicating that HGF may also play a role in immunosuppression of T cell response." (PMID 28548070, 2014).
brain injury (4 papers, 2013 to 2023). Acute and chronic (see also brain INJURIES, CHRONIC) injuries to the brain, including the cerebral hemispheres, CEREBELLUM, and brain STEM. "Inflammatory mediators (IL-6, IL-12p40, HGF, M-CSF, CCL2, and IL-1RA) are associated with both altered consciousness and markers of brain injury." (PMID 38135686, 2023). "For instance, they can be used to deliver growth factors as hepatocyte growth factor (HGF) or fibroblast growth factor (FGF) 21, to improve repair after a spinal cord or brain injury, respectively." (PMID 34200425, 2021). "In a previous study with traumatic brain injury model rats, UC-MSC administration up-regulated neurotrophic factors, such as Bdnf and hepatocyte growth factor, and improved the neurological severity." (PMID 32848614, 2020). "Animals that exercise after brain injury show an increase in the expression of neurotrophic factors, such as BDNF, HGF, and FGF-2, which regulate neuronal survival and differentiation, synaptic plasticity, as well as angiogenesis in the brain." (PMID 24098645, 2013).
cardiac amyloidosis (4 papers, 2023 to 2025). Cardiac amyloidosis is a condition whereby cardiac tissue is infiltrated by amyloid fibrils. "Both decorin and HGF have previously been shown to provide diagnostic information in cardiac amyloidosis." (PMID 41141478, 2025). "The latest data from cardiology oncology show that HGF is a biomarker associated with the prognosis of cardiac amyloidosis." (PMID 40041176, 2025). "The available data on HGF in patients with CA suggest that HGF plays a particularly salient role in amyloid heart disease." (PMID 40570404, 2025).
cardiac hypertrophy (4 papers, 2017 to 2025). "High levels of HGF discriminated between patients with CA and patients with HF with reduced ejection fraction or hypertrophy, and were associated with worse outcomes." (PMID 40570404, 2025). "Activation of the receptor of HGF, Met, induces concentric cardiac hypertrophy in experimental models." (PMID 40570404, 2025). "HGF suppresses myocardial hypertrophy and its down-regulation activity on fibrogenic and hypertrophic genes is associated with improved cardiac function." (PMID 28291817, 2017). "An elevated PVP in the early posttransplant phase correlated with rapid liver hypertrophy along with low portal blood levels of VEGF and elevated peripheral HGF values." (PMID 37047199, 2023). "We demonstrated that the constitutive activation of the Met proto-oncogene, the receptor for hepatocyte growth factor (HGFR), leads to the development of concentric cardiac hypertrophy." (PMID 31052420, 2019). "On the other hand, another transgenic mouse with cardiac specific overexpression of HGF did not develop cardiac hypertrophy, indicating negative regulatory mechanisms on ligand-activated Met receptor signaling." (PMID 31052420, 2019).
clear cell renal cell carcinoma (4 papers, 2022 to 2025). "Alterations in HGF were significantly enriched in high telomeric content samples from kidney clear cell carcinoma (OR = 3.7), brain glioblastoma (OR = 8.3), and prostate acinar adenocarcinoma (OR = 2.8)." (PMID 35227290, 2022). "In addition, median telomeric content of HGF altered samples was significantly higher in brain glioblastoma, kidney clear cell carcinoma, and prostate acinar adenocarcinoma (p<0.001 for all)." (PMID 35227290, 2022). "We also found that CAFs interact uniquely with VM cells and tumor cells via HGF/MET and CSPG4 signaling pathways in clear cell renal carcinoma, and its effect on VM cells is significantly higher." (PMID 38694917, 2024).
colon adenocarcinoma (4 papers, 2016 to 2023). "For example, in BRCA, adenocarcinoma of colon (COAD) and most other tumors, all the six immune cells showed a positive correlation with HGF, indicating that immune cells were activated or recruited by the HGF/c-MET pathway." (PMID 34261467, 2021). "In summary, we show here that cloudberry extract inhibits HGF-induced scattering and migration into a scratch wound in HT29 and HCA7 colon adenocarcinoma cells, which is accompanied by inhibition of Met receptor activation and downstream signaling to the PI3K/AKT and ERK pathways." (PMID 27270323, 2016).
dilated cardiomyopathy (4 papers, 2014 to 2022). Cardiomyopathy which is characterized by dilation and contractile dysfunction of the left and right ventricles. "Delivery of ONO1301, a stable small molecule PGI2 agonist on an epicardial collagen patch in a model of dilated cardiomyopathy, demonstrated expression of Hepatocyte Growth Factor (HGF), Vascular endothelial growth factor (VEGF), Stromal cell-derived factor-1 (SDF-1), and G-CSF." (PMID 35194460, 2021).
ductal carcinoma in situ (4 papers, 2013 to 2021). "HGF can promote the transition from a preinvasive to an invasive phenotype of ductal carcinoma in situ (DCIS) cells." (PMID 34572947, 2021). "Together, these findings implicate HGF-secreting fibroblasts in the progression of ductal carcinoma in situ to invasive cancer." (PMID 25887320, 2015). "Increased collagen IV degradation was also demonstrated, along with increased numbers of invasive outgrowths in three-dimensional cultures of ductal carcinoma in situ cells when in the presence of HGF." (PMID 25887320, 2015). "Normal mammary fibroblasts engineered to secrete HGF have been reported to increase invasiveness of c-met expressing human ductal carcinoma in situ (DCIS) cells in vitro and promote the in vivo transition of nude mice DCIS cell xenografts to invasive carcinomas." (PMID 25880005, 2015).
epilepsy (4 papers, 2020 to 2023). A brain disorder characterized by episodes of abnormally increased neuronal discharge resulting in transient episodes of sensory or motor neurological dysfunction, or psychic dysfunction. "Reduced eotaxin (CCL11) and elevated hepatocyte growth factor (HGF) were associated with an increased risk of epilepsy (OR = 1.904, 95% CI = 1.019–3.561, p = 0.044; OR = 0.641, 95% CI = 0.417–0.984, p = 0.042) when the IVW method was used." (PMID 37470000, 2023). "Another group of genes, CHD2, SCN10A, and TBC1D8, was associated with HGF and PTEN; these two genes are related to synaptic plasticity, neuronal cell survival, and CNS development, as well as related to epilepsy." (PMID 33584793, 2020).
experimental autoimmune encephalomyelitis (4 papers, 2016 to 2023). An autoimmune demyelinating disease of the central nervous system that is produced experimentally in animals by the injection of homogenized brain or spinal cord in Freund's adjuvant. "In experimental autoimmune encephalomyelitis (EAE) models, HGF secreted by MSCs promotes neural cell development and remyelination." (PMID 27406064, 2016). "In experimental autoimmune encephalomyelitis (EAE) this pathway promotes proliferation of classically activated macrophages, suggesting a pro-inflammatory role for HGF." (PMID 27545843, 2016).
fibrosarcoma (4 papers, 2019 to 2025). A malignant mesenchymal fibroblastic neoplasm affecting the soft tissue and bone. "ADAMTS1 decreases fibrosarcoma cell proliferation and migration velocity by disrupting HGF/c-MET signaling." (PMID 35625488, 2022).
hepatoblastoma (4 papers, 2011 to 2024). Hepatoblastoma (HB) is a malignant hepatic tumor and is the most common pediatric liver cancer. "While direct activation of β-catenin by CTNNB1 mutation is common in many tumours, pathologic activation of β-catenin by HGF/c-Met signaling with associated transformation has also been reported in several tumors and its activation has been previously reported in hepatoblastoma." (PMID 21992464, 2011). "The most known agonist of TRPV1 capsaicin (the main component in chili pepper) has been shown to lead to an acceleration of human hepatoblastoma cells (HepG2) pretreated with hepatocyte growth factor (HGF)." (PMID 24204345, 2013). "Here we report an analysis of the role of HGF/c-Met related β-catenin activation and CTNNB1 mutation activation of β-catenin in a large cohort of 84 patients with hepatoblastoma." (PMID 21992464, 2011). "Elevated serum levels of HGF have previously been reported in children following resection of hepatoblastoma." (PMID 21992464, 2011). "For the majority of the hepatoblastoma tumoroids (6 of 9 tested), colony formation was abolished in the absence of the standard growth factors usually included in the media (EGF, FGF10, and HGF) or in the presence of a MEK inhibitor, U0126." (PMID 39567523, 2024).
Hypoalbuminemia (4 papers, 2015 to 2023). The concentration of albumin in the blood circulation is below the lower limit of normal. "The reported emibetuzumab-related AEs were mostly mild or moderate in intensity and the most common were hypoalbuminemia (a known class effect for agents targeting MET or HGF) and constipation." (PMID 29071414, 2017). "The only possibly related AE reported in more than 1 patient for LY2875358 monotherapy was hypoalbuminemia, which has previously been reported as a class-related effect for agents targeting MET/HGF." (PMID 27422720, 2016). "Given the key role that the HGF/MET axis plays in liver development and the role of the liver in albumin synthesis, hypoalbuminemia makes mechanistic sense as an expected event." (PMID 26445503, 2015). "Edema, hypoalbuminemia and pulmonary embolism have been reported at rates higher than control in studies with other antibodies targeting MET or HGF." (PMID 26445503, 2015).
intracerebral hemorrhage (4 papers, 2016 to 2024). A cerebrovascular disorder characterized by bleeding into one or both cerebral hemispheres including the basal ganglia and the cerebral cortex. "Also, significantly more myelinated fibres were present in in intracerebral haemorrhage rats transplanted with HGF/UC‐MSCs than with UC‐MSCs." (PMID 35922965, 2022). "Also, the beneficial effect of HGF/UC‐MSCs on myelination was confirmed in an intracerebral haemorrhage rat model." (PMID 35922965, 2022).
intrahepatic cholangiocarcinoma (4 papers, 2018 to 2025). A carcinoma that arises from the intrahepatic bile duct epithelium in any site of the intrahepatic biliary tree. "During the development of intrahepatic cholangiocarcinoma, activated HSCs transition into myofibroblasts (myCAFs) and inflammatory CAFs (iCAFs), which promote the progression of intrahepatic cholangiocarcinoma through the Has2/HA pathway and HGF/MET pathway, respectively." (PMID 41214328, 2025). "The median pretreatment plasma HGF concentration was 2311 pg/mL (range 1037–8000) and was comparable between HCC and intrahepatic cholangiocarcinoma (ICC) patients." (PMID 30374460, 2018).
liver dysfunction (4 papers, 2011 to 2025). "Among them, the hepatocyte growth factor (HGF), a potential surrogate of liver dysfunction, and the proinflammatory interleukins IL6 and IL15 were most profoundly altered." (PMID 40242314, 2025).
malaria (4 papers, 2017 to 2024). Malaria is a serious and sometimes fatal disease caused by a parasite that commonly infects a certain type of mosquito which feeds on humans. "Cell traversal (hepatocytes) observed in several species of Plasmodium, the causative agent of malaria, was reported to induce HGF secretion, the activation of c-MET by hepatocytes and invasion of these cells, while other Plasmodium spp did not." (PMID 35041723, 2022). "KEGG pathway analysis unveiled several pathways, including “Focal adhesion”, “Cell adhesion molecules, “PI3K–AKT signaling pathway” and the “Malaria” (HGF–MET signaling pathway)." (PMID 38543637, 2024). "Using primary hepatocyte cultures, we investigated the role of Kupffer cell-derived hepatocyte growth factor (HGF) in malaria liver stage infection." (PMID 28220125, 2017). "This work indicates that HGF and Fas signaling pathways are part of an orchestrated host apoptosis response that occurs during malaria liver stage infection, decreasing the success of infection of individual hepatocytes." (PMID 28220125, 2017). "Our results indicate that activation of Kupffer cells by malaria parasites entails the production of HGF that specifically induce apoptosis of infected hepatocytes." (PMID 28220125, 2017). "Furthermore, we found that depletion of liver macrophages abrogated the augmented expression of HGF in the liver induced by infection suggesting that liver macrophages are the main in vivo source of HGF in malaria liver stage infection." (PMID 28220125, 2017). "This work supports the view that HGF plays multiple roles during malaria liver stage infection." (PMID 28220125, 2017). "Moreover, the upregulation of the “Malaria” pathway, and more specifically, the HGF–MET signaling axis within this pathway, might promote a favorable environment for parasite infection by the inhibition of cell apoptosis." (PMID 38543637, 2024).
malignant pleural mesothelioma (4 papers, 2019 to 2024). A malignant neoplasm that arises from mesothelial cells in the pleura and shows a diffuse growth pattern. "When discussing HGF in the context of MPE, it should be mentioned that one Japanese study showed an anti-tumor effect of anti-HGF and NK4 (a HGF fragment - competitive inhibitor of HGF-Met receptor) on malignant pleural mesothelioma." (PMID 31699094, 2019). "Moreover, it has been reported that tumor-associated fibroblasts can boost the progression of malignant pleura mesothelioma through a cytokine network involving fibroblast growth factor-2 (FGF-2), platelet-derived growth factor-AA (PDGF-AA), and hepatocyte growth factor (HGF)." (PMID 38462627, 2024). "Taken together, candidate biomarkers (Galectin-1, Mesothelin, Osteopontin, shed SDC-1, VEGF, MMP-7, HGF, TIMP-1 and NRG1-β1) identified in the current study could be diagnostic biomarkers for distinguishing malignant pleural mesothelioma and metastatic adenocarcinoma from benign patients." (PMID 32731396, 2020). "Furthermore, the blocking of the HGF-MET pathway and angiogenesis by NK4 in malignant pleural mesothelioma significantly attenuates invasion and migration capacities." (PMID 34217156, 2021).